BRAF (B-Raf proto-oncogene, serine/threonine kinase)
Diseases named in the same sentence as BRAF in open-access papers (continued):
Sharing a sentence is not in itself a finding about the gene and the disease.
melanoma (continued). "Although Asians do not have a mutation rate as high as Caucasians, nearly one-third of melanoma patients still have BRAF-sensitive site mutations." (PMID 38335433, 2024). "Forty-six existing tissue samples (34 out of 46 were BRAF/NRAS mutated) of metastatic malignant melanoma from 21 patients that originate from diagnostic testing undertaken at the Klinikum Kassel from January 2015 to September 2022 were analysed." (PMID 38127894, 2024). "BRAF mutations are found in approximately 50% of melanomas and play a crucial role in the disease’s pathogenesis." (PMID 38474231, 2024). "Comprehensive genomic profiling through NGS broadens the scope of targeted therapeutics in melanoma, by identifying patients with mutations beyond the common BRAF V600E, such as gene fusions." (PMID 38470950, 2024). "It was discovered that melanoma tumors frequently carry oncogenic mutations in the BRAF gene and that these tumors depend on the RAF/MEK/ERK pathway." (PMID 38686058, 2024). "Our data suggest that intratumoral activation of RIG-I has the potential to improve cancer immunotherapy in almost half of patients with melanoma susceptible to BRAF/MEK inhibition." (PMID 39165562, 2024). "In parallel, data suggest that the combination of targeted and immunotherapy for metastatic BRAF-mutated (BRAFm) melanoma provides an improvement in progression-free survival relative to either targeted or immunotherapy alone." (PMID 38365756, 2024). "DIA/DIG is known to be linked with BRAF gene mutation, which is a mutation associated with various other neoplasms such as melanoma and glioma." (PMID 39114838, 2024). "The results of this research are important for understanding the etiopathogenesis of melanoma and for future research in the field of melanoma development and the association of BRAF mutations with melanoma occurrence." (PMID 39200941, 2024). "BCL2A1 (B-cell lymphoma 2-related protein A1) is an anti-apoptotic member of the BCL-2 family and is associated with the resistance of melanoma cells to BRAF-targeted therapy." (PMID 39100077, 2024). "The BRAF mutation has been shown to be associated with distant metastases in advanced melanoma and other cancers." (PMID 38730723, 2024). "A possible explanation for the observed association between primary melanoma characteristics and patient outcome is that high-risk pT categories, Clark levels, mitotic counts, and regional lymph node metastases correlate with BRAF V600E nuclear translocation." (PMID 39272837, 2024). "BRAF/MEKi is now the standard of care for BRAF‐mutated melanoma, and three combinations have been developed based on the results of RCTs." (PMID 38087810, 2024). "Mutations in BRAF are found in approximately 50% of melanoma cases and correlate with an increased risk for developing brain metastases." (PMID 39861805, 2024). "Our study also demonstrates that the expression levels of both HDAC10 and SPARC respond to the activity state of mutated BRAF in melanoma cells." (PMID 38650694, 2024). "The cell line used here is Mel Im 22, isolated from cutaneous malignant melanoma of nodular type with a typical BRAF mutation." (PMID 38839791, 2024). "In the phase I trial of advanced solid tumors, one patient with BRAF-mutated PTC during part A and three patients, including two BRAF-mutated melanoma and one BRAF wild-type melanoma in part B, had PR." (PMID 38203795, 2024). "Understanding the mechanisms of RAFi resistance is crucial for improving treatment outcomes in BRAF-mutated melanomas." (PMID 39596009, 2024). "In melanoma, BRAF and NRAS mutations promote cell proliferation by activating the MAPK/ERK pathway, while CDKN2A mutations further enhance tumor cell proliferation by removing inhibition of the cell cycle." (PMID 39581873, 2024). "It is now known that certain subtypes of melanoma are associated with specific mutations (BRAF, KIT, and NRAS mutations)." (PMID 39335684, 2024).
melanoma (continued). "In our batch of melanoma samples, there were 12 samples positive for BRAF V600E (54.6%), with mutational loads ranging from 5% to 48.6%." (PMID 38396984, 2024). "Two lines have BRAF mutation, however, with additional various driver mutations, and 70–88% of primary melanomas are BRAF mutated." (PMID 38719996, 2024). "To shed light on the mechanisms in which RICTOR downregulation plays a role in the early adaptation of cells to BRAFi, we analyzed pathways previously implicated in BRAF/MEKi resistance in multiple melanoma cell lines." (PMID 38755661, 2024). "In patients with BRAF-mutated melanoma, ORR was 43.8% vs. 70% (P=0.04), PFS was 19.2 vs. 11.5 months (p=0.22), and OS was 33.4 vs. 16.4 months for the immunotherapy and targeted therapy groups, respectively (P=0.04)." (PMID 38450188, 2024). "LY3009120 showed a similar significant inhibitory effect on the growth of three RAS-mutated equine and canine melanoma cell lines when compared to the effects observed in the reference cell line A375 (BRAF p.V600E)." (PMID 38397192, 2024). "The BRAF mutation V600E also stimulates melanoma cell invasion in vitro and plays a role in tumor neoangiogenesis in vivo." (PMID 38519031, 2024). "For instance, melanoma cells with the BRAF V600 mutation develop resistance to BRAF inhibitors through metabolic reprogramming after undergoing targeted therapy." (PMID 39609317, 2024). "Mutations in the BRAF gene occur in 50–60% of all melanomas, of which approximately 90% are V600E; in this mutation, the amino acid glutamic acid (E) is substituted by valine (V) at position 600 of the protein." (PMID 39594467, 2024). "Targeted therapies aimed at BRAF V600E-mutated melanoma have shown significant clinical responses, although they are often transient." (PMID 38534309, 2024). "The association between the overexpression of LOXL3 and the transformation of immortalized human melanocytes carrying the BRAF V600E mutation into malignant cells was originally described in an in vitro experiment on melanoma cell lines." (PMID 39273022, 2024). "Dysregulations in PI3K and AKT signalling have also been linked to BRAF inhibitor resistance in melanoma." (PMID 38177660, 2024). "Epigenetic alterations in the CSF-1R promoter region induced CSF-1R up-regulation in melanoma cells with the BRAF mutation." (PMID 38254773, 2024). "We set out to clarify the type, incidence, and Risk ratio of CAEs in patients with melanoma who are being treated with combined BRAF and MEK inhibitors therapy compared with patients receiving BRAF inhibitor alone in this systematic review and meta-analysis." (PMID 39776585, 2024). "Loss-of-function mutations or deletions in NF1 are associated with reduced responsiveness to BRAF inhibitors in BRAF-mutated melanomas." (PMID 38534309, 2024). "In melanoma and to a lesser degree in thyroid carcinoma, BRAF mutational status is a critical biomarker because it predicts response to a specific treatment, namely BRAF +/- MEK inhibition." (PMID 38549938, 2024). "Here, we report the novel role of laminB1, a nuclear structure protein, in regulating the response of BRAF-mutated melanoma cells to vemurafenib." (PMID 39682248, 2024). "In a meta-analysis with an average BRAF mutation prevalence of 47.8% in the included melanoma studies, the risk of death was 1.7 times higher in patients with BRAF mutant melanoma than in patients with BRAF wild-type melanoma." (PMID 39272837, 2024). "In the adjuvant setting, targeted therapies for melanoma substantially reduced the risk of relapse by 53% compared to placebo, leading to the approval of BRAF plus MEK inhibitors as a treatment option for stage III melanoma." (PMID 39336897, 2024). "Of these, the most common are the BRAF and NRAS oncogenes, with 50% of melanomas demonstrating the BRAF mutation (BRAFV600E)." (PMID 38275910, 2024).
melanoma (continued). "Approximately 50% of melanomas harbor a mutation in the BRAF gene, which leads to the constitutive activation of the MEK-ERK signaling pathway, resulting in increased cell proliferation and growth." (PMID 39272803, 2024). "The oncogenic BRAF mutation, found in approximately 40% of melanomas, leads to sustained activation of the MAPK signaling pathway, influencing tumor cell differentiation, proliferation, and metabolism." (PMID 39669561, 2024). "ACAGT-007a was also shown to be effective in killing pancreatic cancer cell lines with different KRAS mutations in addition to the BRAF-positive SK-MEL-28 melanoma cell lines via ERK-dependent apoptosis." (PMID 38500550, 2024). "Data on mechanisms of resistance to BRAF/MEK inhibition are scarce in NSCLC and primarily derived from previous studies conducted in BRAF-mutated melanoma." (PMID 39684685, 2024). "The most burning issue in the therapy of metastatic BRAF‐mutated melanoma is the scarcity of biomarkers predictive of therapy outcome." (PMID 38491825, 2024). "Mutations in BRAF play a major role in driving human cancers, most notably in approximately half of melanoma cases." (PMID 38742856, 2024). "Malignant melanoma is the deadliest form of skin cancer, and about 50% of tumors carry activating mutations (V600E/K) of the BRAF oncogene." (PMID 38755661, 2024). "This is the case with the BRAF V600E mutation and its therapeutic targeting by BRAF inhibitors in colorectal cancer, melanoma, and non-small cell lung cancer." (PMID 39337479, 2024). "In 2018, the FDA approved the combination of dabrafenib and trametinib for adjuvant treatment in patients with melanoma harboring BRAF V600 E/K mutations." (PMID 39529955, 2024). "Another phase II study explored the concomitant combination of dabrafenib plus trametinib and pembrolizumab in patients with stage III resectable melanoma with a BRAF V600E mutation." (PMID 39189198, 2024). "Considering BRAF mutation is expressed in most melanocytic nevi, it is possible that the mutation is acquired in early stages of melanoma development." (PMID 39200941, 2024). "The COMBI-r study reported a 10.8 months overall survival for patients with melanoma brain metastases with BRAF V600E or V600K mutations treated with dabrafenib/trametinib as the first-line therapy." (PMID 39204387, 2024). "In our retrospective analysis, patients with advanced BRAF-mutated melanoma treated with first-line IT treatment displayed significant OS benefits compared with those treated with TT (BRAF plus MEK inhibitors)." (PMID 38450188, 2024). "Mutations in BRAF, especially the V600E mutation, are the most common genetic alterations in melanoma, leading to the constitutive activation of BRAF kinase activity and sustained activation of downstream effectors like MEK and ERK." (PMID 39200315, 2024). "Approximately 50% of melanomas harbor BRAF mutations that trigger the MAPK pathway, driving tumor progression." (PMID 39420203, 2024). "Mechanisms of resistance in BRAF-mutant melanoma are closely linked to tumor heterogeneity and the tumor microenvironment (TME)." (PMID 39336897, 2024). "The discovery of activating NRAS mutations in melanoma in the mid-1980s and the subsequent identification of BRAF mutations in 2002 have been significant milestones in understanding melanoma’s molecular pathology." (PMID 38474231, 2024). "For instance, in melanoma and colorectal cancer and with encorafenib treatment, the presence of baseline BRAF V600E mutations has been identified as a predictor of treatment response." (PMID 38195626, 2024). "BRAF mutations are highly prevalent in melanomas, ranging from approximately 40% to 60% of all reported cases." (PMID 38539548, 2024). "Acquired BRAF mutations have been found in non-Hodgkin’s lymphoma, colorectal cancer, malignant melanoma, and brain tumors, including glioblastoma." (PMID 38674026, 2024).
melanoma (continued). "Inhibitors of RAF kinases, particularly those targeting the BRAF^V600E mutation, have shown significant clinical benefit in melanoma and other cancers harboring this mutation." (PMID 39370455, 2024). "In the present manuscript, we clearly demonstrate in four melanoma cell lines (BRAF-mutated and BRAF-WT) that combinations of BH3 mimetics are strongly effective, while single treatments are largely inefficient." (PMID 38542429, 2024). "A recently published paper retrospectively analysed nearly two thousand patients with metastatic BRAF‐mutated melanoma." (PMID 38491825, 2024). "The treatment sequence for advanced BRAF-mutated melanoma still requires further clinical trials for verification and more mature data regarding OS." (PMID 38450188, 2024). "In cancer patients, BRAF-targeting precision therapeutics are effective against Class I BRAF alterations (p.V600 hotspot mutations) in tumors such as melanomas, thyroid cancers, and colorectal cancers." (PMID 39018217, 2024). "Of note, similar results were obtained using another BRAF-mutated melanoma cell line (the M249 cell line), in which MAPKi led also to a decrease in Glu intracellular concentration." (PMID 38690580, 2024). "Prognostically, compared with the BRAF-mutated NRAS wild-type melanomas, the NRAS-mutated melanomas have been related to more aggressive biological behavior with a higher risk of distant metastasis." (PMID 38247727, 2024). "Here, we found that BRAF inhibitors (BRAFi), typically used to treat melanomas with the BRAFV600E mutation, can prominently promote cell proliferation and erythropoiesis through amplifying MAPK activation via dimerizing with CRAF in wild-type BRAF cells." (PMID 39617757, 2024). "Aside from cellular proximity, we can show the relevance of intact neutrophil-associated protease activity for the melanoma-cell-promoting effect in the context of BRAF/MEK inhibition in vitro." (PMID 38730718, 2024). "BRAF mutations, which occur in approximately 40–60% of melanoma cases, lead to the constitutive activation of MAPK pathway driving uncontrolled cell division and contributing to melanoma initiation and progression." (PMID 39596009, 2024). "This is supported by the identification of BRAF mutations in nevi and primary or metastatic melanoma, suggesting that this mutation is an early event in melanoma genesis, but the prognostic value of BRAF mutation requires further validation." (PMID 38541077, 2024). "Characterize the dermatoscopic signs of second primary melanomas (SPMs) and changes of other documented skin lesions in patients taking Vemurafenib for BRAF V600E mutations." (PMID 38481925, 2024). "Rationale: The response rate to the MEK inhibitor trametinib in BRAF-mutated melanoma patients is less than 30%, and drug resistance develops rapidly, but the mechanism is still unclear." (PMID 38169595, 2024). "Despite the use of BRAF(V600E) targeted drugs in melanoma, the BRAF(V600E) mutation is actually more frequent in melanocytic nevi compared with melanoma." (PMID 39052013, 2024). "Recent studies have demonstrated that PTEN loss co-occurs with BRAF mutations in 44% of BRAF mutant melanomas." (PMID 39200315, 2024). "BRAF mutations are frequently associated with melanoma onset and BRAF inhibitors have been long studied, but pharmacological resistance to these treatments has been reported." (PMID 38399442, 2024). "The clinical trials targeted patients with malignant melanoma, wherein mutations were detected using the “Cobas®BRAF V600 mutation detection kit” to primarily detect the BRAF V600E mutation." (PMID 38167464, 2024). "Both the benign conventional melanocytic nevus and the malignant melanoma of pathway 1 typically harbor a BRAF V600E mutation in approximately 80–90% of cases." (PMID 38247727, 2024).
melanoma (continued). "The BRAF-mutated melanoma cells exhibited varied responses to treatment, including decreased viability and/or induction of a G1 arrest in the cell cycle analysis." (PMID 38730718, 2024). "WRC is activated by EphA2 through RAC1; therefore, WRC is an important intersection in melanoma migration from oncogenic BRAF signaling and Pten loss-mediated signaling." (PMID 38233537, 2024). "About 15–30% of human tumors harbor BRAF mutations, predominantly in 30–60% of malignant melanomas in humans." (PMID 39272320, 2024). "Genetic testing for specific mutations, such as the BRAF V600E mutation in melanoma or EGFR mutations in lung cancer, helps identify targeted therapies that selectively inhibit cancer cell growth and improve patient outcomes." (PMID 38785712, 2024). "Of note, BRAF-V600E mutations are implicated in the growth of melanoma due to activation of downstream MEK/ERK growth pathways." (PMID 39682188, 2024). "Next, we sought to identify gene alterations that were enriched in metastatic vs. primary tumors for each BRAF mutation Class in the 3 cancer types where BRAF mutations are most frequently identified: melanoma, colorectal, and NSCLC." (PMID 38275886, 2024). "A meta-analysis including 400 patients with BRAF-mutated advanced melanoma showed a 65% DCR with rechallenge of BRAF and MEK inhibitors in later lines." (PMID 39064005, 2024). "A significant decrease in GPX-4 and/or FTH-1 expression levels was noted in all three BRAF-mutated melanoma cell lines, with a particularly pronounced effect seen with cabotegravir treatment." (PMID 38338893, 2024). "Given the common occurrence of NF1 mutation in BRAF-WT melanoma, which renders patients unsuitable for BRAF targeting, it is crucial to thoroughly understand NF1-mutated melanoma to guide the development of appropriate treatments for this aggressive subtype." (PMID 38534309, 2024). "NGS allows for the comprehensive screening of multiple genes associated with melanoma in a single experiment, enabling the efficient identification of mutations in key genes such as BRAF, NRAS, and c-KIT." (PMID 38474231, 2024). "The most common mutation in this context, affecting approximately half of melanoma patients, is found in the BRAF gene, predominantly at codon 600 (V600E)." (PMID 39835134, 2024). "BRAF mutations are key oncogenic drivers in various solid tumors, particularly in malignant melanoma, thyroid cancer, colorectal cancer, and NSCLC." (PMID 39529955, 2024). "First, melanoma is characterized by numerous mutations, such as BRAF mutations, but the relationship between PF's activity and these mutations was not explored in this study." (PMID 39399646, 2024). "In a substantial number of melanoma cases, estimated to be around 40% to 50%, activating mutations are observed in the BRAF gene." (PMID 38534742, 2024). "This allowed the comparison of first-line BRAF/MEK therapy or triple therapy in advanced BRAF-mutated melanoma patients in the first-line setting." (PMID 39684531, 2024). "Background/Objective: Dabrafenib and trametinib (D + T) have been approved for the treatment of stage III melanoma with BRAF V600E V600K mutations in an adjuvant setting, based on the results from the COMBI-AD trial." (PMID 39682258, 2024). "The National Comprehensive Cancer Network (NCCN) advocates for BRAF mutation status testing in high-risk melanoma cases to inform clinical management strategies." (PMID 39610923, 2024). "This drug has emerged as a pivotal therapeutic option targeting the MAPK/ERK pathway in various malignancies, including BRAF-mutated melanoma, non-small cell lung cancer and thyroid cancer." (PMID 38473413, 2024). "This study provides evidence of a significant correlation between CTHRC1 and the BRAF(V600E) mutation, suggesting its potential utility as a diagnostic and prognostic biomarker in human colon cancer, thyroid cancer, and melanoma." (PMID 39052013, 2024).